SHMT2 (serine hydroxymethyltransferase 2)
Diseases named in the same sentence as SHMT2 in open-access papers (continued):
Sharing a sentence is not in itself a finding about the gene and the disease.
ovarian cancer (3 papers, 2021 to 2025). A primary or metastatic malignant neoplasm involving the ovary. "The online splicing data from TCGA database (tsvdb.com/index.html) also confirmed expression of multiple SHMT2 variants in ovarian cancer tissues." (PMID 40097394, 2025). "In general, the high expression of SHMT2α and the low expression of SHMT2 in the hypoxia and low-glucose situation may be one of the causes of cisplatin resistance in ovarian cancer patients." (PMID 40097394, 2025). "Moreover, recent findings have uncovered an association between SHMT2 isoform switching and chemoresistance in ovarian cancer." (PMID 40738465, 2025). "However, exact mechanisms underlying discrete roles of SHMT2 isoforms in ovarian cancer require further investigation." (PMID 40097394, 2025). "In addition to expression level, SHMT2 genetic polymorphisms may also influence ovarian cancer susceptibility." (PMID 40738465, 2025). "However, the functions and underlying mechanisms of SHMT2 in ovarian cancer remain rarely studied." (PMID 40097394, 2025). "SHMT2 decreased, while SHMT2α increased stem cell like features of ovarian cancer cells, as identified by spheroid formation ability, expression of stemness markers CD44 and CD133." (PMID 40097394, 2025). "The current study demonstrated that cisplatin-sensitive and cisplatin-resistant ovarian cancer cells expressed discrete SHMT2 isoforms, which was ascribed to the selective utilization of SHMT2 alternative promoters." (PMID 40097394, 2025). "Together, these findings suggest that SHMT2 contributes to ovarian cancer development, prognosis, and therapeutic response through its expression level, genetic variants, and isoform-specific regulatory mechanisms." (PMID 40738465, 2025). "Two SHMT2 isoforms were identified in ovarian cancer tissues, the smaller isoform was upregulated, even though downregulation of total SHMT2 in cisplatin-resistant tissues." (PMID 40097394, 2025). "The current study reported that HIF1α and TFE3 were implicated in the utilization of SHMT2 alternative promoter, resulting in expression of SHMT2 isoforms in cisplatin-resistant ovarian cancer cells under metabolic stress." (PMID 40097394, 2025). "Cisplatin-resistant and -sensitive ovarian cancer cells express distinct SHMT2 isoforms, regulated by alternative promoter usage." (PMID 40738465, 2025). "Collectively, the current study demonstrated that ovarian cancer cells expressed multiple SHMT2 isoforms, which exerted complicated functions." (PMID 40097394, 2025). "Real-time RT-PCR demonstrated that the total SHMT2 mRNA expression was significantly decreased in cisplatin-resistant compared to the cisplatin-sensitive ovarian cancer tissues." (PMID 40097394, 2025). "A case-control study indicated that certain single-nucleotide polymorphisms in the SHMT2 gene, particularly in combination with dietary or genetic factors such as folate status or MTHFR genotype, were associated with altered risk of ovarian carcinoma." (PMID 40738465, 2025). "Our study verified complicated implication of SHMT2 isoforms in ovarian cancer cells." (PMID 40097394, 2025). "SHMT2 was identified to be downregulated in the cisplatin-resistant ovarian cancer tissues." (PMID 40097394, 2025). "The current study demonstrated that SHMT2 isoforms might exert paradoxical functions in ovarian cancer cells." (PMID 40097394, 2025). "However, further studies are needed to dissect, how SHMT2 isoforms exerted paradoxical functions in ovarian cancer." (PMID 40097394, 2025). "Selective utilization of SHMT2 alternative promoter by HIF1α and TFE3 resulted in SHMT2 isoform expression shift, which might be implicated in adaptation of ovarian cancer cells under metabolic stress." (PMID 40097394, 2025). "Expression of SHMT2 was further analyzed using 24 cisplatin-sensitive and 12 cisplatin-resistant ovarian cancer tissues and confirmed the downregulation of SHMT2 in cisplatin-resistant ovarian cancer tissues." (PMID 40097394, 2025).
ovarian cancer (continued). "Identification of selective utilization of SHMT2 alternative promoter by the combination of HIFα and TFE3 in cisplatin-resistant ovarian cancer cells in the current study further strengthen the complicated interlinkage between hypoxia and SHMT2." (PMID 40097394, 2025). "Collectively, regulation of SHMT2 isoform expression via alternative promoter usage by transcription factors HIF1α and TFE3 provides a novel basis and potential drug targets for the clinical treatment of platin-resistant ovarian cancer." (PMID 40097394, 2025). "In addition, the current study demonstrated that SHMT2 alternative promoter usage mediated by HIF1α and TFE3 might represent adaptive response of ovarian cancer cells to metabolic stress." (PMID 40097394, 2025).
Parkinson disease (3 papers, 2018 to 2026). A progressive degenerative disorder of the central nervous system characterized by loss of dopamine producing neurons in the substantia nigra and the presence of Lewy bodies in the substantia nigra and locus coeruleus. "GSEA revealed significant co-enrichment of MRPS11 and SHMT2 in pathways related to the “ribosome,” “Parkinson’s disease,” and “olfactory transduction”." (PMID 41013856, 2025).
squamous cell carcinoma (3 papers, 2023 to 2025). A carcinoma arising from squamous epithelial cells. "Kaplan-Meier survival analysis of clinical tumor samples revealed that patients with adenocarcinoma (AC), squamous cell carcinoma, and SCLC exhibiting high SHMT2 expression had a significantly lower overall survival (OS) than those with low SHMT2 expression." (PMID 40738465, 2025). "In the TCGA datasets of the two main subtypes of NSCLC, adenocarcinoma (LUAD) and squamous cell carcinoma (LUSC), PSAT1, SHMT1, SHMT2, MTHFD1 and MTHFD2 were significantly overexpressed compared to normal lung tissue." (PMID 38515202, 2024).
acute leukemia (2 papers, 2013 to 2022). A clonal (malignant) hematopoietic disorder with an acute onset, affecting the bone marrow and the peripheral blood. "Although acute leukemias are typically highly proliferative, the effect of one-carbon folate pathway inhibition using a novel inhibitor of SHMT1 and SHMT2, RZ-2994, was greater in T-ALL compared to AML." (PMID 34341479, 2022).
bladder transitional cell carcinoma (2 papers, 2021 to 2024). The most common morphologic subtype of urinary bladder carcinoma (over 90% of cases). "In this study, we established an in vitro experimental model by transient interfering with the expression of SHMT2 in human bladder transitional cell carcinoma cells J82 and T24 using siRNA." (PMID 38594513, 2024). "To date, SHMT2 has been reported to be overexpressed in malignant lesions; however, there is no related research in bladder urothelial carcinoma, which was done in this paper for the first time." (PMID 34149818, 2021).
breast invasive carcinoma (2 papers, 2021 to 2024). "Otherwise, UALCAN results indicate that expression of SLC25A32 and SHMT2 correlates with overall survival in breast invasive carcinoma." (PMID 39125744, 2024).
colitis (2 papers, 2019 to 2021). Inflammation of the colon. "SIRT5 desuccinylates and activates SOD1 to eliminate ROS, desuccinylates and activates PKM2 to block macrophage IL-1β production and prevent DSS-induced colitis, and desuccinylates and activates SHMT2 to drive cancer cell proliferation." (PMID 34930316, 2021).
colorectal tumor (2 papers, 2018 to 2025). "Collectively, these data indicate that SHMT2 K95 acetylation is frequently downregulated in colorectal tumors and is associated with increased SIRT3 expression." (PMID 30367038, 2018). "Using an immunohistochemical analysis, we also revealed that levels of SHMT2 were positively correlated with levels of SIRT3 in 309 colorectal tumor samples." (PMID 30367038, 2018). "Expression of the mitochondrial folate metabolism enzymes SHMT2, MTHFD2, and ALDH1L2 was upregulated in colorectal tumor tissues, and their high expression correlated with poor patient prognosis." (PMID 41154660, 2025).
depression (2 papers, 2025). "In summary, the potential role of MRPS11 and SHMT2 in depression, through mitochondrial dysfunction and oxidative stress, offers new insights into the pathogenic mechanisms and potential therapeutic strategies for MDD." (PMID 41013856, 2025). "Given the role of mitochondrial dysfunction in the pathophysiology of depression, MRPS11 and SHMT2 may represent potential therapeutic targets for this condition." (PMID 41013856, 2025).
folate deficiency (2 papers, 2023 to 2025). A nutritional condition produced by a deficiency of FOLIC ACID in the diet. "Immortalized cell models of total SHMT2 loss or folate deficiency exhibit decreased oxidative capacity and impaired mitochondrial complex I assembly and protein levels, suggesting folate-mediated one-carbon metabolism (FOCM) and the oxidative phosphorylation system are functionally coordinated." (PMID 36959541, 2023).
Hepatic steatosis (2 papers, 2024 to 2025). Steatosis is a term used to denote lipid accumulation within hepatocytes. "Interestingly, SHMT2-deficient mice developed simultaneous fatty liver, but when fed a diet high in fat, fructose, and cholesterol, they had significantly less inflammation and fibrosis." (PMID 38347107, 2024). "In mice with hepatic steatosis, reversed serine hydroxymethyltransferase 2 (SHMT2) activity drives glycine depletion and acetaminophen hepatotoxicity." (PMID 39962071, 2025). "Our findings suggest that SHMT2 prevents hepatic steatosis and protects the liver from steatosis damage in mice under chow-fed conditions." (PMID 38347107, 2024). "We concluded that SHMT2 deletion in hepatocytes worsens liver steatosis and injury but reduces inflammation and fibrosis in the AMLN diet treatment." (PMID 38347107, 2024). "The absence of SHMT2 increased serine and glycine levels in circulation, decreased liver methylation potential, and increased susceptibility to fatty liver disease." (PMID 38347107, 2024). "We have further discovered that SHMT2 has a nonlinear function in NAFLD: inhibiting hepatic steatosis but supporting liver fibrosis development." (PMID 38347107, 2024).
liver disease (2 papers, 2024 to 2025). "This indicates that SHMT2 is a metabolic gene that significantly associates with the development and outcome of metabolic syndrome and liver disease in human populations." (PMID 38347107, 2024).
metabolic dysfunction-associated steatotic liver disease (2 papers, 2024 to 2025). Metabolic dysfunction-associated steatotic liver disease (MASLD, formerly known as nonalcoholic fatty liver disease or NAFLD) is a type of liver disease that is not caused by alcohol. "Mouse genetics indicates that serine hydroxymethyltransferase 2 maintains hepatic methylation potential and plays stage-specific roles in the pathogenesis of non-alcoholic fatty liver disease." (PMID 38347107, 2024).
metabolic syndrome (2 papers, 2024 to 2025). A cluster of metabolic risk factors for CARDIOVASCULAR DISEASES and TYPE 2 DIABETES MELLITUS. "Upon conducting a more in-depth analysis of SHMT1, which encodes the cytosolic counterpart of SHMT2, it was observed that the SHMT1 gene SNPs are also significantly associated with human metabolic phenotypes that define metabolic syndrome." (PMID 38347107, 2024). "In contrast, SHMT1 influences lipid metabolism through DNA methylation and adipocyte differentiation in metabolic diseases such as obesity and metabolic syndrome, whereas SHMT2 regulates mitochondrial function, glycine metabolism, and oxidative stress resistance." (PMID 40738465, 2025). "Given the liver’s central role in lipid metabolism, inflammation, and systemic homeostasis, SHMT2 dysfunction may also exacerbate extrahepatic complications, such as metabolic syndrome and cardiovascular comorbidities." (PMID 40738465, 2025).
multiple myeloma (2 papers, 2024 to 2025). "The observation of SHMT2 upregulation in response to RT also applies to multiple myeloma models, underscoring a broader application of sertraline treatment across cancers." (PMID 38160212, 2024). "Notably, the combination of Len with Serine hydroxymethyltransferase inhibitor 1 (SHIN1)—a small-molecule compound that binds to SHMT2, a subunit of the BRISC complex—further enhances the sensitivity of myeloma cells to Len." (PMID 41463377, 2025).
Obesity (2 papers, 2025). Accumulation of substantial excess body fat. "SHMT2 has been implicated in the regulation of glycine levels, which are often decreased in obesity and associated metabolic disorders." (PMID 40738465, 2025). "In contrast, SHMT1 and SHMT2 influence adipose tissue methylation and energy metabolism via distinct mechanisms during the development of obesity." (PMID 40738465, 2025). "The findings reveal that pea fibre may prevent obesity through the SHMT2/glycine/mTOR/PPAR-γ signal pathway." (PMID 40075937, 2025).
oral cancer (2 papers, 2021 to 2022). "Both mRNA and protein expression of SHMT2 in oral cancer cells were higher than that in normal oral keratinocyte." (PMID 33863325, 2021).
anaplastic carcinomas (1 paper, 2024). "It is worth to note that SHMT2 expression was also elevated in benign thyroid adenomas and anaplastic carcinomas compared to normal tissues (GSE27155)." (PMID 38272883, 2024).
autoimmune disease (1 paper, 2021). A disorder resulting from loss of function or tissue destruction of an organ or multiple organs, arising from humoral or cellular immune responses of the individual to their own tissue constituents. "Since it has been recently shown that an inactive form of SHMT2 dimer has the capacity to bind and inhibit BRISC, control of the SHMT2-BRISC interaction may represent a new target to control autoimmune diseases." (PMID 33692797, 2021).
bipolar disorder (1 paper, 2025). A disorder of the brain that causes unusual shifts in mood, energy, activity levels and the ability to carry out day-to-day tasks. "The mRNA expression of SHMT2 has also been associated with bipolar disorder, further supporting the NMDA receptor (NMDAR) hypothesis of bipolar disorder." (PMID 41013856, 2025).
bladder tumor (1 paper, 2024). "High expression levels of SHMT2 promote the proliferation and migration of malignant bladder tumor cells in vitro while inhibiting tumor cell apoptosis." (PMID 38594513, 2024). "In addition, it was observed that the low levels of SHMT2 expression blocked the bladder tumor cell cycle in the G2/M phase, which lead to decreased of cell proliferation and increased apoptosis." (PMID 38594513, 2024).
chronic myeloid leukemia (1 paper, 2023). "In addition, haploid chronic myeloid leukemia cells (HAP1, wild-type) or HAP1 cells lacking SHMT2 expression (ΔSHMT2) were cultured for 4 doublings in either low-folate or folate-sufficient culture media." (PMID 36959541, 2023).
Cognitive impairment (1 paper, 2025). Abnormal cognition is characterized by deficits in thinking, reasoning, or remembering. "Mutations in SHMT2 have been associated with a novel developmental syndrome characterized by cognitive impairment, motor dysfunction, and progressive heart disease." (PMID 40738465, 2025). "However, direct evidence indicates that mutations in SHMT2 are linked to novel neurodevelopmental syndromes characterized by cognitive impairment, motor dysfunction, and structural brain abnormalities." (PMID 40738465, 2025).
colorectal adenocarcinoma (1 paper, 2020). The most common type of colorectal carcinoma. "Kaplan–Meier survival analysis showed a significantly shorter overall survival in colorectal adenocarcinoma patients with high ILF3, PHGDH, or SHMT2 gene expression." (PMID 31772275, 2020).
diabetes (1 paper, 2021). "The associations between PMVK and diabetes, and SHMT2 and diseases of the salivary gland, were replicated in the UKB and PMBB respectively (PMVKP = 0.00727, SHMT2P = 0.005515)." (PMID 33750777, 2021).
dysplasia (1 paper, 2020). A usually neoplastic transformation of the cell, associated with altered architectural tissue patterns. "In this study, we utilized human OSCC tissue microarrays to investigate the expression of SHMT2 among human normal oral mucosa, dysplasia tissues, and OSCC by immunohistochemistry." (PMID 33163414, 2020).
End Stage Liver Disease (1 paper, 2019). Final stage of a liver disease when the liver failure is irreversible and LIVER TRANSPLANTATION is needed. "SHMT2 might be a therapeutic target to improve the prognosis of patients with end-stage liver disease who are going to receive subtotal hepatectomy and liver transplantation." (PMID 31828098, 2019).
Ewing sarcoma (1 paper, 2025). A small round cell tumor that lacks morphologic, immunohistochemical, and electron microscopic evidence of neuroectodermal differentiation. "Genetic depletion of serine hydroxymethyltransferase 2 dramatically impairs tumor growth in a xenograft model of Ewing sarcoma." (PMID 40698729, 2025). "Furthermore, when we analyzed the effect of CRISPR/Cas9-mediated gene inactivation on the viability of the 769 cell lines included in the DepMap Chronos dataset, we found that Ewing sarcoma ranks first among all solid tumors for dependence on SHMT2." (PMID 40698729, 2025). "To define the biological consequences of the overexpression of one-carbon metabolism genes, we generated two Ewing sarcoma cell lines (SK-ES-1 and TC-71) expressing control shRNAs or shRNAs targeting SHMT1 or SHMT2." (PMID 40698729, 2025). "To further define the relative impact of inhibiting one-carbon metabolism on these cytosolic pathways in Ewing sarcoma cells, we first tested whether providing exogenous metabolites can rescue cells from the growth suppression caused by pharmacologic inhibition of SHMT1 and SHMT2." (PMID 40698729, 2025). "The inability to survive in the prolonged absence of SHMT2 suggests that Ewing sarcoma cells are “addicted” to elevated activity of SHMT2." (PMID 40698729, 2025). "Notably, although we could readily generate cell lines constitutively expressing shSHMT1, Ewing sarcoma cells did not survive constitutive SHMT2 targeting such that we had to use a doxycycline-inducible vector for expressing these shRNAs." (PMID 40698729, 2025).
Glucose intolerance (1 paper, 2025). Glucose intolerance (GI) can be defined as dysglycemia that comprises both prediabetes and diabetes. "Dietary glycine deficiency impairs insulin secretion, reduces islet mass, and worsens glucose intolerance, while overexpression of serine hydroxymethyltransferase 2 (Shmt2), a key glycine biosynthetic enzyme, increases circulating glycine, enhances insulin output, and improves glucose control." (PMID 42037784, 2025).
ischemia (1 paper, 2019). A hypoperfusion of the BLOOD through an organ or tissue caused by a PATHOLOGIC CONSTRICTION or obstruction of its BLOOD VESSELS, or an absence of BLOOD CIRCULATION. "The present study examined the expression of SHMT2 in an IR mouse model and showed that impaired SHMT2 expression induced JNK activation and promotes apoptosis, exacerbating hepatic ischemia-reperfusion injury." (PMID 31828098, 2019).
Leigh syndrome (1 paper, 2021). A progressive neurological disease defined by specific neuropathological features associating brainstem and basal ganglia lesions. "Supporting our current proposal that metformin might operate as a small-molecule inhibitor of SHMT2, metformin has recently been reported to mimic the ability of serine catabolism blockade to ameliorate disease progression in a murine model of neuromuscular Leigh syndrome." (PMID 34439169, 2021).
metastatic tumors (1 paper, 2017). "Notably, the significant correlation between ASCT2 or SHMT2 and nodal status, T stage and survival indicates a connection of higher metabolic activity and associated protein expression in metastatic tumors and tumors with further progression." (PMID 29020998, 2017).